USP8P1 (USP8 pseudogene 1)
Synonyms: KIAA0055-hom; D84394.7; USP8P
Gene: Processed pseudogene on chromosome 6 (31,275,572 to 31,278,754, forward strand). Ensembl gene ENSG00000214892.
Diseases named in the same sentence as USP8P1 in open-access papers:
USP8P1 is named in the same sentence as 1 disease in open-access papers, as found by Europe PMC text mining. Sharing a sentence is not in itself a finding about the gene and the disease.
USP8P1 shares sentences with these, for which no sentence is quoted: psoriasis (2 papers).